AR (androgen receptor)
Diseases named in the same sentence as AR in open-access papers (continued):
Sharing a sentence is not in itself a finding about the gene and the disease.
osteosarcoma (continued). "Altogether, our data confirm that U2OS osteosarcoma cells represent a pertinent model for HCS-based functional screening of potential inhibitors of the transcriptional activity of the androgen receptor." (PMID 32560058, 2020). "In conclusion, the identification of a link between CDK11 and AR transcriptional regulation provides a means for prioritizing key targets in potential osteosarcoma therapeutic interventions." (PMID 28262798, 2017). "We then compared the expression levels of AR in primary osteosarcoma specimens from cases with different responses to preoperative chemotherapy." (PMID 28262798, 2017). "A correlation between AR and survival of osteosarcoma patients implicates the high expression of AR as a potential biomarker for prognosis." (PMID 28262798, 2017). "We examined the correlation between CDK11 expression and AR expression in both osteosarcoma cell lines and primary osteosarcoma patient tumor tissues." (PMID 28262798, 2017). "High expression of AR has been shown in osteosarcoma cell lines and tissues, and its inhibition attenuates cell growth and viability." (PMID 28262798, 2017). "Reconstructed network of the differentially expressed genes pointed to the AR as key to CDK11 signaling in osteosarcoma." (PMID 28262798, 2017). "Kaplan-Meier analysis showed that osteosarcoma patients had a lower disease free survival in the high CDK11 or AR expressions group compared with patients in the low CDK11 or AR expressions group (P < 0.001 and P = 0.012)." (PMID 28262798, 2017). "The functional roles of AR in growth/viability and migration of osteosarcoma cell lines were evaluated." (PMID 28262798, 2017). "The Spearman’s correlation coefficient of CDK11 and AR staining patterns in osteosarcoma TMA was 0.701 (P < 0.001)." (PMID 28262798, 2017). "Our results are in line with a recent study showing knockdown of AR inhibited the viability of osteosarcoma cells." (PMID 28262798, 2017). "As osteosarcomas tend to occur most commonly in young people with a higher incidence in males, we then evaluated the relationship between AR expression and gender or age." (PMID 28262798, 2017). "Both CDK11 and AR expression showed adverse predictive value for osteosarcoma patients in disease free survival rates." (PMID 28262798, 2017). "Four out of eight osteosarcoma tissue samples showed both AR and CDK11 proteins as highly expressed." (PMID 28262798, 2017). "In an effort to validate and further understand the AR connection, we experimentally examined the expression and relationship between CDK11 and AR in osteosarcoma cell lines and patient tissues." (PMID 28262798, 2017). "To determine the role of AR in osteosarcoma, we evaluated the effects of AR siRNA and AR specific inhibitor (bicalutamide) in osteosarcoma cell lines." (PMID 28262798, 2017). "Western blot analysis confirmed low-expression of AR in osteosarcoma cells transfected with AR siRNA and showed the AR expression closely correlated with cell viability." (PMID 28262798, 2017). "Thereby, the results suggest that AR inhibitor bicalutamide significantly depressed the growth and progression of osteosarcoma cells." (PMID 28262798, 2017). "In two osteosarcoma cell lines, the protein level of AR was affected by the DBC1 expression level, but the expression of DBC1 was not affected by AR expression level." (PMID 26249023, 2015). "There was significant correlation between the expression of DBC1 and AR protein levels as shown in immunohistochemical staining in human osteosarcoma tissue samples and Western blotting in osteosarcoma cells." (PMID 26249023, 2015). "The cut-off points for the immunohistochemical staining scores (IHC scores) of DBC1 or AR immunostaining were determined at the most likely point for the prediction of death of osteosarcoma patients." (PMID 26249023, 2015).
osteosarcoma (continued). "Proliferation of osteosarcoma cell lines in vitro was stimulated by estradiol, progesterone, and 5 alpha-dihydrotestosterone; whereas growth was abrogated by AR antagonists as fulvestrant, mifepristone, and hydroxiflutamide." (PMID 25595907, 2015). "Similarly, AR exhibited a high expression rate of 60.0% (60/100) in osteosarcoma, markedly higher than that in normal tissues (10.0%, 3/30, P < .001), and its mean H-score (170.8 ± 40.8 vs 80.6 ± 20.5, P < .001) also showed a significant difference." (PMID 41517748, 2026). "Estrogen receptors (ER-∝, ER-β), progesterone receptor (PR), and androgen receptor (AR), have been previously identified on human osteosarcoma (OSA) cells, and are considered to influence tumor growth, but their expression and role in canine OSA is unknown." (PMID 36288137, 2022). "As osteoblasts are commonly involved in the osteosarcoma pathological process, the oncogenic role of AR may be partly carried out by regulating bone homeostasis." (PMID 28262798, 2017). "Based on the hypothesis generated by gene network reconstruction, we performed experiments to evaluate the relationship between CDK11 and AR in osteosarcoma." (PMID 28262798, 2017). "Meanwhile, we checked whether AR siRNA transfection could affect the migration of osteosarcoma cells in a wound-healing assay." (PMID 28262798, 2017). "Both CDK11 and AR shared the same expression pattern in osteosarcoma cell lines and tumor tissues." (PMID 28262798, 2017). "In this study, we identified AR as a potential key player in CDK11 signaling in osteosarcoma." (PMID 28262798, 2017). "Given that multiple agents targeting AR are currently in preclinical or clinical development, the results from this study may lead to another tool in the chemotherapy for osteosarcoma clinical trials." (PMID 28262798, 2017). "In addition, osteosarcoma patients with high expression of AR showed good response to preoperative chemotherapy." (PMID 28262798, 2017). "Similar results were found in osteosarcoma cells treated with AR inhibitor." (PMID 28262798, 2017). "AR protein was highly expressed in various osteosarcoma cell lines and patient tumor tissues." (PMID 28262798, 2017). "We tested the effect of this AR inhibitor, bicalutamide, on osteosarcoma cells." (PMID 28262798, 2017). "The important role of AR in skeletal growth has already been well described, which may contribute to its oncogenic role in osteosarcoma." (PMID 28262798, 2017). "In this study, by differential gene expression we found several genes that might be the AR downstream target genes in osteosarcoma, such as cyclin G2, CDC20, Caspase-8, JNK." (PMID 28262798, 2017). "We present here a first demonstration of the connection between CDK11 and AR in osteosarcoma." (PMID 28262798, 2017). "CDK11 increased transcriptional activation of AR gene in osteosarcoma cell lines." (PMID 28262798, 2017). "Moreover, there was a close relationship between CDK11 and AR staining patterns in osteosarcoma TMA representing various types of osteosarcoma." (PMID 28262798, 2017). "Therefore, additional study with a large number of cases is needed to confirm the clinical significance of the expression of DBC1 and AR in osteosarcoma patients." (PMID 26249023, 2015). "In addition, the knock down of DBC1 and AR decreased the invasion activity and inhibited invasion-related signaling of osteosarcoma cells." (PMID 26249023, 2015). "The effects of antiandrogens on mutant AR(F876L), AR(W741L), and AR(T877A) were studied in transactivation assays in human U2-OS osteosarcoma cells transiently transfected with expression vectors encoding the corresponding mutant AR and an androgen-responsive luciferase reporter gene construct." (PMID 26137992, 2015). "Therefore, our findings suggest that DBC1 is involved in the progression of osteosarcoma by stabilizing AR." (PMID 26249023, 2015).
osteosarcoma (continued). "Therefore, this study investigated the role of DBC1 and AR in osteosarcoma by using human osteosarcoma tissue samples and osteosarcoma cell lines." (PMID 26249023, 2015). "In conclusion, this study demonstrated that the expression of DBC1 and AR could be usable as prognostic indicators of osteosarcoma." (PMID 26249023, 2015). "AR+ has been demonstrated in 28.5% (8/28) to 50.8% (33/65) of osteosarcomas [S36,S37]." (PMID 25595907, 2015). "We hypothesize that high expression of YAP and AR may be associated with advanced tumor stage, metastasis, and poorer progression-free survival (PFS), making them valuable prognostic indicators and potential therapeutic targets in osteosarcoma." (PMID 41517748, 2026). "Moreover, therapeutic strategies targeting both YAP and AR may provide new avenues for osteosarcoma treatment." (PMID 41517748, 2026). "Thereby, AR inhibitors may be effective in osteosarcoma treatment both in vivo and in vitro." (PMID 28262798, 2017). "However, little is known about AR involvement in osteosarcoma." (PMID 28262798, 2017). "The significance of targeting AR signaling as a putative therapeutic in osteosarcoma is unknown." (PMID 28262798, 2017). "Moreover, the inhibition of the proliferation and invasion activity of osteosarcoma cells with the knock-down of DBC1 or AR suggested that the DBC1-AR pathway could be usable as a new therapeutic target in the treatment of osteosarcoma patients." (PMID 26249023, 2015). "Therefore, we investigated the role of DBC1 and AR and their relationship in osteosarcoma." (PMID 26249023, 2015). "Therefore, present results suggest that suppression of DBC1 and/or AR could be a therapeutic stratagem for the treatment of osteosarcoma patients." (PMID 26249023, 2015). "In terms of survival analysis, we observed that high expression of YAP and AR significantly shortened PFS in osteosarcoma patients, further confirming the potential of YAP and AR as prognostic biomarkers." (PMID 41517748, 2026). "We observed that both YAP and AR were more frequently overexpressed in advanced-stage (Stage III–IV) and metastatic osteosarcomas, suggesting a potential role in driving tumor invasiveness and dissemination." (PMID 41517748, 2026). "Expressions of AR and CDK11 were also shown to be significantly higher in osteosarcoma cell lines compared to normal osteoblast cell lines." (PMID 28262798, 2017). "In osteosarcoma cell lines, U2OS and SaOS2, the knock down of DBC1 and AR with siRNA significantly reduced cellular proliferation and inhibited proliferation-related signaling." (PMID 26249023, 2015). "This study also showed a positive correlation between the protein levels of AR and DBC1 by immunohistochemistry in human osteosarcoma tissues and by western blot in osteosarcoma cells." (PMID 26249023, 2015). "In human osteosarcoma tissues, the expression of DBC1 was mainly localized in the nuclei of tumor cells and AR was expressed both in the nuclei and cytoplasm." (PMID 26249023, 2015). "Confocal analysis showed co-localization of DBC1 and AR mainly in the nuclei of osteosarcoma cells and immunoprecipitation (IP) showed direct binding of DBC1 to AR." (PMID 26249023, 2015). "In osteosarcoma patients, 49% (17/35) and 49% (17/35) of cases were included in DBC1-positive and AR-positive groups, respectively." (PMID 26249023, 2015). "Given the current lack of research on the combined role of YAP and AR in osteosarcoma, this study aims to fill that gap." (PMID 41517748, 2026). "As expected, DSRCT demonstrated significant AR upregulation compared to these other sarcoma samples from chondrosarcoma, well-differentiated and dedifferentiated liposarcoma, and osteosarcoma (p < 0.01–p < 0.0001) but did not surpass the levels observed in PC." (PMID 35650195, 2022).
osteosarcoma (continued). "Both AR siRNA and bicalutamide significantly suppressed osteosarcoma cell viability and growth, but not migration." (PMID 28262798, 2017). "Because clinical data suggests that the expression of DBC1 and AR may be involved in the progression of osteosarcomas despite the limited number of cases, we evaluated the effects of a knock-down of DBC1 and AR in osteosarcoma cells." (PMID 26249023, 2015). "In addition, siRNA-mediated knock-down of AR and DBC1 inhibited proliferation and invasion activity of osteosarcoma cells, which correlated with inhibition of proliferation and invasiveness-related signaling." (PMID 26249023, 2015). "In conclusion, this study has shown that DBC1 is involved in the stabilization of AR protein and DBC1-AR pathways might be involved in the progression of osteosarcoma." (PMID 26249023, 2015). "However, a therapy to promote CDK11p58 activation to reduce AR activity may not be a good strategy as CDK11—the isoform was not reported—has been reported to promote AR expression and activation in osteosarcoma." (PMID 35326402, 2022).
Anxiety (24 papers, 2013 to 2026). Intense feelings of nervousness, tension, or panic often arise in response to interpersonal stresses. "Subsequently, the anxiety level is positively associated with the length of CAG repeats in AR in men." (PMID 36159923, 2022). "Conversely, in male studies comparing wild-type and AR deficient male rats gonadectomized right after birth, gonadectomized rats exhibited lower anxiety-like behavior in both groups compared to their gonadally intact male counterparts." (PMID 36159923, 2022). "Studies involving various lines of AR-deficient mice and rats further support the role of AR in influencing anxiety- and depressive-like behaviors." (PMID 32727567, 2020). "Several studies also reported that AR gene polymorphism was associated with vulnerability to major depression or anxiety." (PMID 31480771, 2019). "Previous studies indicated the positive linkage between androgen and depression symptom severity, and other studies also reported that AR gene polymorphism was associated with vulnerability to major depression or anxiety." (PMID 31480771, 2019). "Estrogen and androgen receptor agonists have generally been shown to decrease time spent in open arms, which is generally associated with anxiety." (PMID 31402896, 2019). "Carriers of the shorter, most common, allele of the AR gene’s GGN microsatellite polymorphism had fewer anxiety-related symptoms, which was consistent with previous studies, but in our study this was not significant following Bonferroni correction." (PMID 28158988, 2017). "Our study further supports that a dysregulation of AR PN/IN in cortical areas, presumably caused by disturbed serotonergic signalling, is one possible cause of generalized anxiety giving new insights into underlying mechanism of anxiety." (PMID 30677060, 2019). "Therefore, obese women with anxiety symptomatology could benefit from androgen receptor blockers or weight loss as an additive therapy." (PMID 31333520, 2019). "The role of androgen signaling in the regulation of anxiety-related behavior was demonstrated by administration of the androgen receptor antagonist flutamide, but also using the animal model of testicular feminization mutation and androgen receptor knockout mice." (PMID 30127767, 2018). "In conclusion, functional modulation of androgen receptor signaling leads to significant alterations in male zebrafish behavior, particularly affecting fear responses, aggression, and anxiety-related behaviors." (PMID 41823821, 2026). "Together, these studies indicate a robust role of androgen acting via AR in influencing anxiety- and depressive-like behaviors in rodents." (PMID 32727567, 2020). "Studies with testicular feminized rats and mice, that have life-long dysfunctional androgen receptor signaling, have demonstrated increased aspects of anxiety in both species." (PMID 29434234, 2018). "Aiming to solve this anxiety, in the following we analysed miR-19a’s effect on AR expression and activity." (PMID 23451058, 2013). "Beyond 5-HT1 AR-Erk interactions, c-myc, a key downstream effector of Erk, plays a significant role in hippocampal neurogenesis and regulates miRNA synthesis, including miR- 203 and miR- 17–92, which are involved in anxiety regulation." (PMID 40266546, 2025). "Anxiety-like behavior in female offspring after prenatal androgen exposure as well as intra-AMY microinjections of T appears to be mediated by the effect of T via AR on the fetal amygdala." (PMID 36159923, 2022). "Our finding that the most common allele of the AR microsatellite, GGN23, was associated with fewer anxiety-related symptoms was consistent with previous work, though in our study this wasn’t significant following correction for multiple hypotheses." (PMID 28158988, 2017).
Anxiety (continued). "The GGN microsatellite in exon 1 of the AR gene showed modest nominally significant associations between a dichotomous (homozygous major allele GGN23 carried by 70% of individuals vs rest) measure and two outcomes: child IQ (r = −0.104, p = 0.046) and anxiety symptoms (r = 0.096, p = 0.040)." (PMID 28158988, 2017). "For this purpose, we used a mouse model lacking AR selectively in the nervous system in order to analyze the effects of specific neural AR mutation on temporal order memory for visual objects, novel object recognition, anxiety-related behaviors and circulating levels of corticosterone." (PMID 26849367, 2016). "Several brain regions have been implicated as potential sites at which androgens might interact with AR to regulate the HPA axis and anxiety- and depressive-like behaviors." (PMID 32727567, 2020). "We found limited support for the previously observed association between the AR gene’s exonic GGN microsatellite polymorphism and anxiety-related symptoms, but we found no significant results for two previously studied repeats in the AP2-β transcription factor gene." (PMID 28158988, 2017). "We found that neural AR deletion selectively impaired the processing of temporal information for visual objects, without affecting classical object recognition or anxiety-like behavior and circulating corticosterone levels, which remained similar to those in control males." (PMID 26849367, 2016).